RAC1 (Rac family small GTPase 1)
Diseases named in the same sentence as RAC1 in open-access papers (continued):
Sharing a sentence is not in itself a finding about the gene and the disease.
lymphoma (24 papers, 2011 to 2025). A malignant (clonal) proliferation of B- lymphocytes or T- lymphocytes which involves the lymph nodes, bone marrow and/or extranodal sites. "Through analysing our RNA-Seq dataset for the presence of intrinsically up-regulated gene expression signatures in Eμ-Myc/RelAT505A lymphomas, we discovered elevated expression of genes encoding components of the RAC1/RHOA signalling pathway, something also seen in Eμ-Myc/c-Rel−/− lymphomas." (PMID 36240067, 2022). "Constitutively active Rac1 stimulates bad phosphorylation, suppressing drug-induced caspase activation and apoptosis in human lymphoma cells." (PMID 39941828, 2025). "For lymphoma, CIT again revealed a one-tier system based on RAC1 expression, with the appertaining cut-off of ≤193 counts identifying lymphoma cases (p = 0.007)." (PMID 35955742, 2022). "Overall, our study suggests that RAC1 occupies a key position in a signaling pathway by which lymphoma cells grow, migrate and die." (PMID 36552804, 2022). "We analyzed Rac1 activation using specific anti–Rac1-GTP Abs in the lung in which lymphomas developed." (PMID 35326399, 2022). "SAMSN1, typically highly expressed in lymphomas, is a splice variant of HACS1 which promotes RAC1-dependent membrane ruffle formation." (PMID 34570764, 2021). "In lymphoma cells, overexpression of Bcl2 inhibits Rac1-mediated apoptosis, but in pheochromocytoma-12 cells, these interactions are considered to be protective." (PMID 31277234, 2019). "Double deletion of Cdc42 and Rac1 even completely abrogated the development of lymphoma up to 28 weeks." (PMID 30558116, 2018). "To explore the relevance of a 3D lymphoma cell culture in AmCA hydrogels to tumor growth in vivo, we compared excised tumor tissue with the 2D- and 3D-lymphoma cell cultures in terms of Tiam1, Rac1, and c-Myc expression." (PMID 29416753, 2018). "We performed expression analyses for STAT3pTyr705 and STAT3pSer727, total STAT3, Bcl-2pSer70), total Bcl-2 and Rac1, in lysates obtained from cells isolated from biopsies from 41 patients diagnosed with lymphomas." (PMID 26430964, 2015). "One report using lymphoma cells demonstrated direct inhibition of apoptosis through Rac1-stimulated phosphorylation of the Bcl-2 family member, Bad, which occurred in an Akt-independent manner." (PMID 26132202, 2015). "NPM-ALK signals in part through Rac1 thereby contributing to the pathogenesis of ALK-positive human lymphomas." (PMID 23874639, 2013). "Moreover, Tiam1 and Rac1 were overexpressed in a 3-D model of lymphoma, where treatment with Tiam1/Rac1 inhibitor NSC23766 overcame chemoresistance to doxorubicin." (PMID 32322580, 2020).
lymphoma (continued). "Importantly, Rac1 protein overexpression levels correlate with a shorter overall survival in MCL patients, suggesting an active role for Rac1 in the pathophysiology of this lymphoma." (PMID 30558116, 2018). "Similarly, Rac1 and Tiam1 seem to be crucial in the infiltration of adult T cell leukemia/lymphoma (ATL)." (PMID 30558116, 2018). "In addition, the few tumors that developed from shRac1 lymphoma cells were found to express Rac1, suggesting that incomplete silencing of Rac1 facilitated the proliferation of these cells." (PMID 30558116, 2018). "We recently reported that the interaction of Bcl-2 and Rac1 was localized at the mitochondria, and that mono-site phosphorylation of Bcl-2 at serine 70 (Bcl-2pSer70) stabilized its anti-apoptotic activity and was a poor prognostic indicator in human lymphomas." (PMID 26430964, 2015). "Therefore, we wished to determine whether activation of Rac1 might play an indirect role in the contribution of Vav1 to development of Lymphomas." (PMID 35326399, 2022). "In addition, both CDC42 and RAC1 contribute to lymphoma cell dissemination in mouse models of ALCL." (PMID 31248017, 2019). "RAC1-GTP levels were unchanged in tissues from Rosa26 VAV1 mice, whereas ERK phosphorylation was increased in lymphomas." (PMID 37174676, 2023). "For example, in alveolar macrophages pulmonary fibrosis, mitochondrial import and direct electron transfer from cytochrome c to Rac1 modulates mitochondrial H2O2 production, and Bcl2 overexpression in lymphoma cells inhibits Rac1-mediated apoptosis." (PMID 34063353, 2021). "In this review we present the latest advances in the field with particular focus on the role of the most studied typical RHO GTPases such as CDC42, RAC1, and RHOA and the atypical RHOH in the initiation or progression of human lymphomas." (PMID 31248017, 2019). "For example, the recruitment of Tiam1 (T lymphoma invasion and metastasis), a GEF for Rac1, is important for epithelial polarization as it promotes perijunctional actin polymerization and tight junctions formation." (PMID 26872368, 2016). "This second messenger is known to bind a Rac1 specific GEF, Tiam1 (T lymphoma invasion and metastasis)." (PMID 26872368, 2016). "Results also highlight the potential utility of a signature involving Bcl-2 overexpression, Rac1 activation and STAT3 phosphorylation for stratifying clinical lymphomas based on disease severity and chemoresistance." (PMID 26430964, 2015). "The link between Rac1 and NPM1 was previously only described in nucleophosmin-anaplastic lymphoma kinase (NPM-ALK)-positive lymphomas." (PMID 23874639, 2013). "Neither manual examination, STRING analysis nor functional annotation clustering using our phosphoproteomic data gave any further insights into whether RHOA or RAC1 signalling might be up-regulated in Eμ-Myc/RelAT505A lymphomas (not shown)." (PMID 36240067, 2022). "Rac1-GTP levels did not change in tissues from Rosa Vav1 mice expressing the transgenic Vav1, while ERK phosphorylation increased in the lymphomas, suggesting that signaling pathways are evoked." (PMID 35326399, 2022). "In malignant lymphomas, FilGAP expression was significantly higher in B-cell lymphomas than PTCL, and the immunohistochemical scores were positively correlated with cytoplasmic Rac1 scores in FL and DLBCL, but not in PTCL." (PMID 25641953, 2015).
triple-negative breast carcinoma (23 papers, 2017 to 2025). An invasive breast carcinoma which is negative for expression of estrogen receptor (ER), progesterone receptor (PR), and human epidermal growth factor receptor 2 (HER2). "We previously reported that TNFAIP2 activates Rac1 to promote triple-negative breast cancer (TNBC) cell proliferation, migration, and chemoresistance." (PMID 39532855, 2024). "For instance, ITGB4 promotes triple-negative breast cancer to resist DNA damage via TNFAIP2/IQGAP1/RAC1, and thus accelerates the drug resistance of tumor cells." (PMID 38831335, 2024). "In triple negative breast cancer cells reduction of tumorigenic phenotypes is accompanied by reduced expression of RAC1, alpha-actinin, vinculin and FAK65 and silencing of vinculin reduces cell viability and decreases tumor volume in animal models." (PMID 33633298, 2021). "Overexpression of Rac1-GTPase was observed in triple-negative breast cancer." (PMID 40728965, 2025). "ITGB4 promotes triple-negative breast cancer (TNBC) drug resistance via TNFAIP2/IQGAP1/RAC1." (PMID 37787041, 2023). "In addition, activation of the RASAL2/ARHGAP24/RAC1 module slows triple-negative breast cancer (TNBC) progression, and RASAL2 overexpression is related to poor prognosis and tumor recurrence in TNBC." (PMID 36159573, 2022). "Our study showed higher Rac1 expression in triple-negative breast cancer MDA-MB-231 cells than that in MCF-7 cells, which may explain why MDA-MB-231 cells showed stronger migration and invasion abilities." (PMID 32547389, 2020). "We found that both Rhein and derivative 4F down-regulated expression in both cell lines, but derivative 4F worked at a lower concentration than did Rhein and had a more obvious effect on human triple-negative breast cancer MDA-MB-231 cells with high Rac1 expression." (PMID 32547389, 2020). "Furthermore, compared to MCF-7 cells, derivative 4F showed a more obvious effect on human triple-negative breast cancer MDA-MB-231 cells with high Rac1 expression." (PMID 32547389, 2020). "RASAL2 also activates RAC1 to promote triple-negative breast cancer progression." (PMID 33817145, 2019). "Moreover, the Tiam1/Rac1 signaling axis contributes to tumorigenic progression in triple-negative breast cancer by mediating the acquisition of integrin-directed metastasis-associated tumor cell phenotypes." (PMID 29416753, 2018). "In triple-negative breast cancer, decreased expression of miR-371b-5p drives tumor progression through CSDE1/RAC1 regulation." (PMID 40302797, 2025). "IQGAP1 mediates RAC1 activation by TNFAIP2 and promotes triple-negative breast cancer (TNBC) drug resistance." (PMID 37787041, 2023). "TNFAIP2 promotes triple-negative breast cancer (TNBC) drug resistance and DNA damage repair via RAC1." (PMID 37787041, 2023). "ERK3 knockdown significantly decreased the levels of both basal and EGF-induced GTP-bound CDC42 and RAC1 in primary (HMEC) and triple-negative breast cancer (MDA-MB231) mammary epithelial cells, respectively." (PMID 37057894, 2023).
Intellectual disability (22 papers, 2016 to 2025). "Consistently, patients with RAC1 mutations display neurodevelopmental defects, such as microcephaly, cerebellar atrophy, and intellectual disability." (PMID 36681682, 2023). "Mutations in Rac1 that result in loss or gain of function are associated with intellectual disability." (PMID 36214784, 2022). "Defects in Rho GTPases signaling pathways are also heavily implicated in neurodevelopmental disorders, including missense mutations in Rac1 that cause intellectual disability and an Arp2/3 mutation associated with schizophrenia." (PMID 34269176, 2021). "Dysfunctional Rac1/Cdc42 has been associated with aberrant synaptic plasticity and intellectual disability." (PMID 31379509, 2019). "The CYFIP1 gene is known to interact with the WAVE regulatory complex and proteins from two genes: RAC1, disruption of which causes an autosomal dominant form of intellectual disability, and FMR1, the causative gene for fragile X syndrome." (PMID 30909440, 2019). "Misregulated RhoA, Rac1/Rac3 and cdc42 activity has been linked with intellectual disability (ID) and other neurodevelopmental conditions that comprise ID." (PMID 29925821, 2018). "Loss-of-function mutations in RAC1 and other genes of the Rac signaling pathway have been implicated in the pathogenesis of Intellectual Disability (ID)." (PMID 29740022, 2018). "Mutation in oligopherinin 1, a RhoGAP for RhoA, Rac1, and Cdc42, leads to reduction in spine length and number of mature spines accompanied by resulting phenotypes including intellectual disability, epilepsy, microcephaly, ataxia, and hyperactivity." (PMID 27795858, 2016). "Dysregulation of MEGAP, another RhoGAP for Rac1 and Cdc42, has also been associated with intellectual disability and microcephaly." (PMID 27795858, 2016). "GAP activity is required to regulate Rac1 activation since alterations in this pathway have been implicated in intellectual disability, a neurodevelopmental disorder characterized by defects in network connectivity and unbalanced excitation and inhibition in the cerebral cortex." (PMID 33495243, 2021). "For example, morphology of dendritic spines is heavily altered in conditions of aberrant CaMKII/Tiam1/Rac1 activity, which might collaborate to intellectual disability of patients bearing mutations of the ATRX-encoding gene." (PMID 33240883, 2020). "We reasoned that this intellectual disability-related C18Y mutation in Rac1 may prevent Kalirin and Trio-mediated upregulation of Rac1 activity during LTP and thus inhibit LTP induction." (PMID 30042656, 2018). "Downstream of Rac1 in actin polymerization, mutations in PAKs and WASF1 can cause macrocephaly, seizures, intellectual disability, or ASD." (PMID 37255534, 2023). "Rac1 mutations associated with intellectual disability impair synaptic plasticity, and variants in the RhoGEF TRIO can cause ASD, intellectual disability, schizophrenia, or macrocephaly, with severe phenotypes predicted by Rac1 overactivation." (PMID 37255534, 2023). "Rac1 has also been identified in Autism-Spectrum Disorder (ASD) and Intellectual Disability (ID) animal models with Rac1 being implicated in many genetic abnormalities in ASD/ID." (PMID 34054432, 2021). "The CYFIP1 gene also interacts with the protein from the RAC1 (RAS-related c3 botulinum toxin substrate 1; OMIM # 602048) gene, disruption of which causes an autosomal dominant form of intellectual disability." (PMID 30909440, 2019). "RAC1-related intellectual disability also includes macrocephaly and one individual was reported to have ASD." (PMID 30909440, 2019). "Growing evidence suggests that disruption of the Rac1 signaling pathway at glutamatergic synapses contributes to Autism Spectrum Disorder/intellectual disability (ASD/ID)-related behaviors seen in animal models of ASD/ID." (PMID 30042656, 2018).
Intellectual disability (continued). "For example, TRIO SR8 variants are linked to developmental delay and macrocephaly in humans and cause increased Rac1 (GEF1) activity in cells, whereas most mutations in the GEF1 domain are linked to mild intellectual disability, microcephaly, and reduced Rac1 activity in cells." (PMID 35963430, 2022). "However, it has been recently reported that either hypo or hyperactivity of Rac1 could lead to neuritogenesis impairment, giving arise to intellectual disability." (PMID 33240883, 2020).
cutaneous melanoma (21 papers, 2016 to 2025). A primary melanoma arising from atypical melanocytes in the skin. "In cutaneous melanoma, the most prevalent activating RAC1 mutation is a point mutation resulting in the protein change of P29S, which results from a C > T nucleotide substitution associated with UV damage." (PMID 41109929, 2025). "The Rac1 P29S hotspot mutation in cutaneous melanoma is associated with resistance to MAPK pathway inhibitors (MAPKi) and worse clinical outcomes." (PMID 41109929, 2025). "Mutations in RAC1 P29, the third most frequently mutated codon in human cutaneous melanoma, can activate the PAK, AKT and ARF/MRTF signaling pathways and lead to melanocytic mesenchymal phenotypic switching." (PMID 37277447, 2023). "In the context of BRAF inhibition, our approach identified Rac1/cytoskeletal signaling as an important biological process underlying intrinsic drug resistance in cutaneous melanoma with oncogenic BRAF." (PMID 35581546, 2022). "Rare gain-of-function mutations in RAC1 drive drug resistance to targeted BRAF inhibition in cutaneous melanoma." (PMID 36271142, 2022). "The third most common mutation found in cutaneous melanoma occurs within the small GTPase RAC1, in which the P29S mutation induces a constitutively active form of the RAC1 protein." (PMID 34066022, 2021). "In general, frequency of RAC1 mutations and CNVs in our skin melanomas dataset is 5.1 and 5.9%, respectively." (PMID 32850962, 2020). "RAC1 P29 is the third most commonly mutated codon in human cutaneous melanoma, after BRAF V600 and NRAS Q61." (PMID 31257073, 2019). "Now, next generation sequencing has identified a number of cancer-associated mutations along the length of the Rac1 protein, with Rac1 being identified as a driver mutation in head and neck squamous cell carcinoma and cutaneous melanoma." (PMID 27104658, 2016). "For example, the mutex analysis between RAC1 and NRAS in skin melanomas confirms the relevance of the role of RAC1, which is co-mutated with NRAS, in gain-of-function oncogenic GTP mediated events." (PMID 26860319, 2016). "A third newly discovered oncogene as being linked to cutaneous melanomas is RAC1." (PMID 34630850, 2021). "The hyperactivation of PAK1 in cutaneous melanomas may be further attributed to activating mutations in RAC1, but also to even more common activating mutations in NRAS and the inactivation of RAS inhibitor NF1, as RAS-induced transformation involves and depends on the activation of RAC1 and PAK1." (PMID 37830586, 2023). "Here we delineate mechanisms of Rac1-driven MAPKi-resistance and identify strategies to inhibit the growth of this class of cutaneous melanomas." (PMID 41109929, 2025). "Overall, these data highlight the importance of RAC1 in driving growth or innate drug resistance to BRAFi in cutaneous melanoma cells." (PMID 36271142, 2022). "A mutated version of Rac1, RAC1P29S, is a well-described driver of MAPK inhibitor resistance and metastasis in cutaneous melanoma." (PMID 35581546, 2022). "Fluorescence results further confirmed the colocalization of FMRP protein and RAC1 mRNA in the cytoplasm of acral melanoma and cutaneous melanoma cells." (PMID 35534866, 2022). "To test the importance of RAC1 for drug resistance, we knocked down RAC1 in a panel of nine BRAFV600E cutaneous melanoma cell lines and assessed their growth in the presence or absence of a targeted inhibitor of BRAFV600E, vemurafenib (VEM)." (PMID 36271142, 2022). "In this review, we focus on the role of RAC1 in cutaneous melanoma metastasis, advances in our understanding of key signaling pathways altered by activated RAC1, and its potential clinical therapeutic implications in metastatic cutaneous melanoma treatment." (PMID 34827551, 2021).